MTSS1 (MTSS I-BAR domain containing 1)
Diseases named in the same sentence as MTSS1 in open-access papers (continued):
Sharing a sentence is not in itself a finding about the gene and the disease.
tumor (67 papers, 2007 to 2025). "Among them, MTSS1 is a potent tumor metastasis suppressor that is implicated in the metastasis suppression of various human cancers." (PMID 40066676, 2025). "Our in vitro studies demonstrated a stronger influence of MTSS1 loss with increasing tumour aggression in cancer cells with a ‘pure’ HER2+ phenotype (HER2+/ER−/PR−)." (PMID 29497041, 2018). "The Metastasis suppressor protein 1 (MTSS1) plays a key role in the maintenance of cell–cell adhesions and its loss correlates with tumour progression in a variety of cancers." (PMID 29497041, 2018). "MTSS1 is highly expressed in primary tumours and its loss has been found to correlate with metastasis and poor prognosis in different types of cancer." (PMID 29497041, 2018). "In this study, starting from our mouse model of PDAC, we show that inflammation in PDAC is correlated with loss of a recently discovered metastatic tumor suppressor gene, metastasis suppressor 1 (MTSS1)." (PMID 28146435, 2017). "Our data suggest that the desmoplasia found during even the beginning stages of tumor formation eventually causes the downregulation of MTSS1 in PDAC epithelial cells." (PMID 28146435, 2017). "Our data suggest that the desmoplastic stroma that is a hallmark of PDAC suppresses MTSS1 activity, aiding tumor cell dissemination that can lead to metastasis." (PMID 28146435, 2017). "Tumor-associated genes, MTSS1, NKX6-2, and BTG2 had CpGs that were highly significant in heavy smokers but showed little or no significance in light smokers." (PMID 27935972, 2016). "The adapter protein metastasis suppressor 1 (MTSS1) is implicated as a tumor suppressor or tumor promoter, depending on the type of solid cancer." (PMID 25996952, 2015). "We also reported that MTSS1 expression was associated with tumour grade (p = 0.024), lymph node metastasis (p = 0.010) and overall survival (p = 0.035)." (PMID 21696600, 2011). "A statistically significant association was observed between MTSS1 expression level and tumor size, histology and Lauren's classification." (PMID 20712855, 2010). "Our results showed that loss of MTSS1 expression was associated with large tumor size, low differentiation, deep invasion level, advanced tumor stage, the presence of nodal metastasis, and poor outcome in patients who underwent gastrectomy." (PMID 20712855, 2010). "Positive associations between MTSS1 expression and other clinicopathologic features, such as tumor size, depth of tumor invasion, status of lymph nodes, TNM stage, differentiation and Lauren's classification were indicated." (PMID 20712855, 2010). "Analysis of mRNAs obtained from 5 classic and 5 desmoplastic tumor specimens revealed that all of them expressed Mtss1, and specifically the same basic splice variants within the region of exons 11–13." (PMID 17925019, 2007). "MTSS1 has a potential tumor suppressor function, which may explain the association of greater expression (and lesser methylation) of MTSS1 with reduced MRD22 and reduced risk of relapse." (PMID 29928480, 2018). "Our findings define the cerebellum, and Purkinje cells in particular, as a paradigm to further test the function of Mtss1, to unravel how its functional properties are structurally encoded, and how they may relate to tumor cell biology." (PMID 17925019, 2007). "Although MTSS1 was expressed in some HER2+ molecular subtypes, we observed its expression was markedly decreased in clinical tumour samples with the HER2+/ER−/PR− phenotype, suggesting hormonal androgen expression may mitigate for the loss of MTSS1 tumour suppressor functionality." (PMID 29497041, 2018). "In LUAD, MTSS1 enhances proliferation and invasion, and immune surveillance evasion, while in LUSC, MTSS1 acts as a tumor suppressor by inhibition of these processes." (PMID 41441397, 2025). "Dysregulation of the DNMT3b gene leads to complete or partial removal of methyl groups from the promoters of the MTSS1 tumor-suppressive genes, which contributes to the development of HCC." (PMID 41602133, 2025).
tumor (continued). "It has been shown that miR-28-5p can promote tumor progression by increasing proliferation and inhibiting apoptosis via the suppression of MTSS1 (Metastasis Suppressor 1), which acts as a tumor suppressor." (PMID 40563399, 2025). "Several microRNAs (miR-96, miR-182, miR-29a, miR-411, miR-23a, miR-15b, and miR-135b) downregulate MTSS1,thereby promoting tumor growth, invasion, and metastasis in prostate, hepatocellular, non-small cell lung, osteosarcoma, and colorectal cancers." (PMID 39625546, 2024). "A firmly established tumor suppressor function of MTSS1 is to control actin dynamics and cell adhesion by affecting cancer cell motility." (PMID 39625546, 2024). "This apparent dichotomy has led to questions regarding the exact role of MTSS1 in tumor progression." (PMID 39625546, 2024). "MTSS1 is a tumor-suppressive gene that functions in the inhibition of metastasis via regulating actin dynamics." (PMID 39519115, 2024). "Analysis of a published single-cell RNA-seq (scRNA-seq) dataset of murine LUAD55 revealed the expression of both Mtss1 and Aip4 in tumor cells." (PMID 36810288, 2023). "This is most likely related to the release of its suppressive role in tumor dissemination following MTSS1 downregulation." (PMID 37920825, 2023). "In the mice with reconstitution of human immune cells, MTSS1 knockdown obviously enhanced tumor growth." (PMID 36810288, 2023). "Gene expression was evaluated in treated and untreated tumor cells; it was observed that the treatments with EC (300 μM) induced higher expression of the anti-proliferative genes Cdh1, Mtss1, Pten, Bmrs, Fat1, Smad4, and Nrf2." (PMID 37687058, 2023). "Metastasis-suppressor 1 (MTSS1) is a membrane-interacting scaffolding protein that regulates the integrity of epithelial cell–cell junctions and functions as a tumor suppressor in a wide range of carcinomas." (PMID 36871754, 2023). "Taken together, MTSS1 seems to suppress tumor metastasis in NPC primarily by another mechanism than targeting EMT." (PMID 37920825, 2023). "MTSS1 downregulation in tumor cells resulting from EGFR–KRAS activation stabilizes PD-L1 and enhances immune evasion." (PMID 36810288, 2023). "The patients with weaker MTSS1 expression displayed improved objective response rates to ICB therapy as compared to those with stronger MTSS1 expression, corroborating the role of MTSS1 to regulate PD-L1 expression and tumor immune evasion." (PMID 36810288, 2023). "Acting in post-Golgi recycling pathways, this protein, deemed a tumor suppressor, enhances the trafficking of MTSS1 (metastasis suppressor protein 1) to the cell’s surface." (PMID 37762375, 2023). "In summary, downregulation of MTSS1 correlates with advanced tumor stages and poor prognosis in NPC." (PMID 37920825, 2023). "Mtss1 overexpression significantly inhibited tumor growth in immunocompetent C57BL/6J mice and prolonged animal survival." (PMID 36810288, 2023). "MTSS1 protein binds to actin and promotes cytoskeletal organization, which inhibits the tumor cell metastatic capacity by inhibiting epithelial-to-mesenchymal transition." (PMID 37687058, 2023). ",369 miR-182-5p can control the growth of various kinds of tumors via metastasis suppressor 1 (MTSS1);370, 371, 372 MTSS1 has been correlated with tumor metastasis and progression in different cancers by complex interactions with the actin cytoskeleton." (PMID 35071748, 2022). "Previous studies reported MTSS1 as a tumor and/or metastasis suppressor whose expression is negatively correlated with poor prognosis in some solid tumors, while the specific mechanism of low MTSS1 expression in LUAD is little reported." (PMID 36496997, 2022). "Here, we further verified that MTSS1 functions as a tumor suppressor by impairing cell proliferation, migration and metastasis, and large number of clinical samples were used to confirm that low expression of MTSS1 in LUAD is associated with poor survival." (PMID 36496997, 2022).
tumor (continued). "Consistently with previous findings that MTSS1 is a tumor/metastasis suppressor, our study reveals that the LINC00491/MTSS1 axis facilitates tumor malignant progression via activating Wnt/β-catenin signaling." (PMID 36496997, 2022). "Further experiments in LUAD cell lines and mouse models confirmed that LINC00491 facilitates cell proliferation, migration and tumor metastasis through Wnt signaling via degrading MTSS1." (PMID 36496997, 2022). "Suggesting a role as a tumor/metastasis suppressor, low MTSS1 expression correlated with advanced stage and was an independent prognostic parameter for shorter survival in several solid tumor entities [82−86]." (PMID 34029637, 2021). "The multifunctional protein MTSS1 acts as a tumor and/or metastasis suppressor whose downregulation was associated with a poor prognosis in several solid tumor entities." (PMID 33782537, 2021). "Confirming the tumor-suppressive role of Mtss1 in CML, its experimental re-expression inhibited colony formation in semi-solid media and decreased leukemic burden in recipient mice." (PMID 33782537, 2021). "Recently, the role of the MTSS1 in tumor development, especially in invasion and metastasis, has been reported." (PMID 32913477, 2020). "We found, somewhat surprisingly, that increased expression of MTSS1 seems to be a relatively common feature of primary tumours." (PMID 30858428, 2019). "MTSS1, another mRNA regulated by this lncRNA has been well documented as a tumor suppressor controlling migration and invasion in OC with involvement in the EGF pathway." (PMID 31842477, 2019). "MTSS1 functions as a tumor suppressor in certain human cancers, including lung, bladder, prostate, and gastric cancers." (PMID 30224667, 2018). "miR-708-5p expression also negatively correlated with two tumor suppressors, metalloproteinase inhibitor 3 (Timp3) and metastasis suppressor protein 1 (Mtss1) levels, leading the authors to conclude miR-708-5p acts as a transformative promoter in liver cells." (PMID 29050362, 2017). "Next, (–) control and siMTSS1 PANC-1 cells were plated on Matrigel-coated transwell membranes in order to determine if MTSS1 knockdown had any effect on tumor cell invasion." (PMID 28146435, 2017). "A higher level of MTSS1 mRNA was significantly correlated with tumor number (P = 0.035), presence of HCC satellite (P = 0.019), incomplete or no encapsulation (P = 0.008), presence of vascular invasion (P = 0.042) and advanced TNM stage (P = 0.033)." (PMID 27230279, 2016). "In HCC, miR-135a transcribed by forkhead box (FOX) M1 induces the development of portal vein tumor thrombus by promoting metastasis, and inhibiting metastasis suppressor 1 (MTSS1)." (PMID 27486383, 2016). "In this study, we first screened the metastasis-related genes in residual HCC tissues, and found that MTSS1 was located in the central position of the tumor gene network." (PMID 27230279, 2016). "The synchronous alteration of MMP2 with MTSS1 suggests that MTSS1 promotes tumor metastasis by targeting MMP2." (PMID 27230279, 2016). "Several studies demonstrated miR-182 involvement in HCC and metastasis, by controlling the expression of genes with tumor suppressor activity, such as the metastasis suppressor MTSS1, Cebpa, ephrinA5, and FOXO1." (PMID 26728044, 2016). "Decreased MTSS1 expression levels were significantly correlated with larger tumor size, deeper invasion, increased lymphatic metastasis and advanced tumor stage." (PMID 25295101, 2014). "Protein expression of the three target genes (FOXF2, RECK, MTSS1) was significantly higher in stable low miR-182-5p expressing xenograft tumor tissues." (PMID 23383207, 2013). "In summary, our study provides a possible novel molecular mechanism for the frequent reduction in expression of the MTSS1 tumor suppressor in various types of human cancers." (PMID 24318128, 2013). "In keeping with this notion, we report here that the tumor suppressor MTSS1 is a novel substrate of β-TRCP." (PMID 24318128, 2013).
tumor (continued). "In patients suffering from esophageal squamous cell carcinoma, the levels of MTSS1 transcript correlated with tumor-grade lymph node metastasis and overall survival; thereby, patients with high levels had a favorable prognosis and hepatocellular carcinoma." (PMID 22926221, 2012). "MTSS1 was often highly expressed in normal tissue, while drastically reduced MTSS1 expression was shown in the tumor cells." (PMID 22681717, 2012). "Our study suggests a model of tumor progression in which elevated miR-182 expression and subsequent down-regulation of MTSS1 promotes aggressiveness of HCC." (PMID 22681717, 2012). "Grade 3/4 tumours (13.82 ± 5.13) had significant reduced levels of MTSS1 compared to grade 1/2 tumours (48.19 ± 16.07) (p = 0.024)." (PMID 21696600, 2011). "Our functional studies have demonstrated that the MTSS1 over-expression resulted in a dramatic reduction in tumour cell migration, invasion and growth, and an increase in cell adhesion." (PMID 21696600, 2011). "Kaplan-Meier analysis demonstrated that patients with high levels of MTSS1 expression in their tumours showed a longer overall survival time (30.00 ± 3.70 months), compared with lower expression levels group (18.00 ± 2.78 months) (p = 0.035)." (PMID 21696600, 2011). "In this study, we assessed the expression levels of MTSS1 in tumours and its matched adjacent non-tumour tissues obtained from 105 ESCC patients." (PMID 21696600, 2011). "A highly significant link was also seen between MTSS1 expression and nodal status, tumour grade and overall survival." (PMID 21696600, 2011). "Lower mRNA expression level of MTSS1 was observed in tumour tissues (27.42 ± 7.32) when compared to the normal background tissues (57.38 ± 13.61), although the difference was only marginally statistically significant (p = 0.054)." (PMID 21696600, 2011). "In the 825 cases of GC with tumor size (<6 cm), 265 (32.1%) presented MTSS1 expression, while only 56 (22.7%) of 247 cases of GC with tumor size (≥6 cm) presented MTSS1 expression (P = 0.005)." (PMID 20712855, 2010). "Moreover, ectopically expressed MTSS1/S322A inhibited cell proliferation and migration more efficiently compared with wild-type MTSS1, indicating a fast turnover of the MTSS1 protein in vivo and/or an altered post-translational regulation in tumor cells." (PMID 39625546, 2024). "MTSS1 was originally identified as a tumor suppressor in bladder carcinoma." (PMID 36871754, 2023). "Instead, a slight suppression of tumor growth was seen after the MTSS1 knockdown." (PMID 36810288, 2023). "MTSS1 downregulation resulted in the suppression of anti-tumor CD8+ T cells in LUAD." (PMID 36810288, 2023). "MTSS1 could participate in cancer progression or tumor metastasis in a variety of organ sites, most likely through an interaction with the actin cytoskeleton." (PMID 38021156, 2023). "Additionally, for in vivo experiments, the xenograft tumor model verified that the overexpression of MTSS1 reversed the proliferation ability of the LUAD cell in vivo, enhanced by LINC00491’s overexpression." (PMID 36496997, 2022). "With few exceptions, MTSS1 acts as a tumor/metastasis suppressor in solid cancers." (PMID 33782537, 2021). "Given the long latency between initial tumor cell development and metastasis in PDAC, it is likely multiple factors from the cancer-associated fibroblasts could influence MTSS1 levels in PDAC cells over time." (PMID 28146435, 2017). "This suggested that MTSS1 functions as a specific metastasis suppressor protein which regulates cell invasion and migration, as opposed to a canonical tumor suppressor protein which would also regulate cell proliferation and tumor growth." (PMID 28146435, 2017). "We tested MTSS1 expression in tumor tissues from HCC patients." (PMID 27230279, 2016). "MTSS1 was up-regulated in residual tumor after palliative resection." (PMID 27230279, 2016).
tumor (continued). "Taken together, our findings suggest that MTSS1 might have a context-dependent function and could act as a tumor suppressor, which is pharmacologically targetable in AML patients." (PMID 25996952, 2015). "This suggests that MTSS1 has a tumor suppressing function in hematopoietic malignancies." (PMID 25996952, 2015). "Moreover, the authors demonstrated that the multi domain adapter molecule MTSS1 functions as a tumor suppressor in vivo." (PMID 25996952, 2015). "MTSS1 was positive in the cytoplasm of tumor and normal liver cells." (PMID 22681717, 2012). "For better understanding the potential role of miR-182 in HCC progression, we analyzed its correlation with some clinicopathological variables including age, sex, HBV infection, AFP, tumor number, tumor size, expression of MTSS1, histological grade, portal vein invasion and recurrent time." (PMID 22681717, 2012). "Several lines of evidence have indicated that the expression of MTSS1 could be down-regulated in solid tumours, whereas up-regulation of MTSS1 expression has also been observed in one other tumour type." (PMID 21696600, 2011). "Importantly, we detected high expression of MTSS1 in adjacent normal epithelium but drastically reduced MTSS1 expression in the tumor cells." (PMID 20712855, 2010). "Previous study reported that down-regulation of MTSS1 expression might correlate with the transition of tumor cells from distinct epithelium-like morphology to less differentiated carcinomas." (PMID 20712855, 2010). "Thus, strategies aiming to increase MTSS1 expression or stabilize the protein could be favorable for immune checkpoint therapy to enhance anti-tumor immunity." (PMID 39625546, 2024). "RNA-Seq of the liver, which had the highest tumor frequency, showed that the expression of 71 genes was specifically altered in DASPO−/− mice compared with that in B6 mice; these genes included RGS 1, MTSS1, and SMARCD 1, which are associated with DLBCL development." (PMID 39718666, 2024). "Thus, absence of the negative influence on the CDAP2/cortactin complex could be one mechanism behind the increased migratory capacity of tumor cells in late-stage cancers, where MTSS1 is silenced." (PMID 39625546, 2024). "Hence, MTSS1 inhibits PD-L1 expression and regulates tumor immune evasion." (PMID 36810288, 2023). "LINC00491/MTSS1/β-catenin may act as a complex to facilitate tumor progression." (PMID 36496997, 2022). "MTSS1 may thus play a wider role in the response to drugs with the potential to eliminate malignant cells, which may be of relevance not only for the application of targeted therapy in AML, but also for other tumor entities in which downregulation of MTSS1 plays a role." (PMID 33782537, 2021). "Thus, the data from solid tumors suggest that MTSS1 may not only be a prognostic AML biomarker but that it may in fact act as an oncogene-specific tumor suppressor in AML." (PMID 25996952, 2015). "However, the exact role of Mtss1 might depend on the cell context and disease type as several reports have recently reported a possible tumor-promoting function." (PMID 25996952, 2015). "Taken together, these observations indicate that aberrancies in the MTSS1 degradation pathway, either by elevated expression of β-TRCP, or hyper-activation of CKIδ, may possibly downregulate the MTSS1 tumor suppressor to facilitate tumor cell growth and cancer progression." (PMID 24318128, 2013). "In addition, the tumor thrombus in small hepatic vein also showed low expression of MTSS1." (PMID 22681717, 2012). "In addition, cmvIL-10 upregulated the expression of matrix metalloproteinases (MMPs) such as MMP-3, MMP-9, and MMP-10, while downregulating metastasis suppressor 1 (MTSS1) in BC cells, which may facilitate tumor cell dissemination and increase metastatic potential." (PMID 40001942, 2025). "Studies have shown that MTSS1 is downregulated in LUAD, leading to upregulation of PD‐L1, impaired function of CD8(+) T cells and accelerated tumour progression." (PMID 39865544, 2025).